VANGL1 (VANGL planar cell polarity protein 1)
Diseases named in the same sentence as VANGL1 in open-access papers (continued):
Sharing a sentence is not in itself a finding about the gene and the disease.
tumor (25 papers, 2013 to 2026). "For example, in gastric tumor cells, Vangl1 drives tumor cell invasiveness and metastasis and binds to the C-terminal domain of KAI1 (CD82), a tetraspanin glycoprotein." (PMID 35646914, 2022). "Previous investigations showed a high tumor expression level of the VANGL-1 gene in CRC patients compared with normal tissues." (PMID 33672900, 2021). "FRAT1 and FRAT2 are tumor promoting genes whereas VANGL1 is a tumor suppressor gene which involved in the Wnt/ß-catenin signaling pathway and thus posses as a molecular target of nobiletin." (PMID 32212785, 2020). "VANGL1 knock-down further blocked tumor growth after exposure to the same radiation dose (P < 0.001)." (PMID 33228740, 2020). "Genes such as IL6, GAB1, and VANGL1, were upregulated both in the tumor buds and in the microenvironment." (PMID 28687755, 2017). "Indeed, both Vangl1 and Vangl2 are dysregulated in diverse tumor types and, consistent with its role in mediating cell motility events in development, Vangl contributes to cancer cell migration, invasion, and metastasis [reviewed in]." (PMID 35646914, 2022). "Besides, the expression of circ_VANGL1 and SOX4 was downregulated, while miR-145-5p was upregulated in xenograft tumor tissues with doxorubicin treatment, circ_VANGL1 knockdown, and co-treatment of doxorubicin and circ_VANGL1 knockdown." (PMID 34258391, 2021). "In conclusion, the main results of this study highlight that the expression of the tumor VANGL1 gene is an independent prognostic biomarker and could be considered a potential predictor for detecting malignancy risk in CRC patients." (PMID 33672900, 2021). "However, it is unclear whether this interaction is required for Vangl1-mediated tumor cell behaviors in this context." (PMID 35646914, 2022). "Thus, VANGL1 could be suggested as a potential biomarker for the prediction of tumor malignancy and targeted therapy in CRC." (PMID 33672900, 2021). "It is well recognized that VANGL1 interacts with the C-terminal domain of a tumor metastasis suppressor, KAI1, therefore VANGL1 is also termed KITENIN (KAI1 C-terminal interacting tetraspanin)." (PMID 33228740, 2020). "Additionally, VANGL1 gene expression levels have been suggested to play a critical role in CRC progression and to be notably related to tumor stages and LNM." (PMID 33672900, 2021). "Thus, it seems that the VANGL1 gene may interact with VEGF-A and HIF1A signaling and enhance tumor malignancy." (PMID 33672900, 2021).
cancer (17 papers, 2010 to 2026). A tumor composed of atypical neoplastic, often pleomorphic cells that invade other tissues. "The cancer-promoting effects of VANGL1 have been associated with influencing the function of KAI1, ErbB4-c-Jun and Dishevelled (Dvl)-PKC signaling." (PMID 33228740, 2020). "Interestingly, Vangl1 has been reported to be upregulated in the HBV-related cancer HCC, and associated with the invasion capacity of HCC cells." (PMID 33441627, 2021). "The cancer-promoting effects of VANGL1 on cell proliferation and invasion have been identified in colorectal and glial malignancies." (PMID 33228740, 2020). "Mechanistically, VANGL1 integrated Wnt/Notch/mTOR signaling with cancer stemness and angiogenesis." (PMID 42294338, 2026). "From a subset of gene products found upregulated on the surface of MCF10A-KRasG12V, the xenotropic and polytropic retrovirus receptor 1 (XPR1) from the formation of cellular protrusions network and the vang-like protein 1 (VANGL1) from the cancer network were selected for cross-validation." (PMID 27894102, 2016).
genetic diseases (1 paper, 2024). "Along the same line, mutations in the human VANGL1 and VANGL2 genes have been linked to genetic diseases characterized by neural tube closure defects." (PMID 38403249, 2024).
VANGL1 also shares sentences with these, for which no sentence is quoted: adenocarcinoma (2 papers); colon adenoma (2); glioma (2); invasive breast carcinoma (2); adenoma (1); colorectal adenocarcinoma (1); colorectal tumours (1); cystic fibrosis (1); lupus nephritis (1); Lymph Node Metastasis (1); malignant glioma (1); neural tube defect (1); pancreatic cancer (1); Parkinson disease (1); pituitary tumor (1); rhinosinusitis (1); scoliosis (1); systemic lupus erythematosus (1); Wilms tumor (1).